HDAC9 (histone deacetylase 9)
Diseases named in the same sentence as HDAC9 in open-access papers (continued):
Sharing a sentence is not in itself a finding about the gene and the disease.
Stroke (continued). "For example, the International Stroke Genetics Consortium (ISGC) and the Wellcome Trust Case Control Consortium 2 (WTCCC2) were the first to report that rs11984041 of HDAC9 is significantly associated with large-vessel ischaemic stroke in European populations." (PMID 28145521, 2017). "In conclusion, this study indicates that HDAC9 contributes to endothelial cell injury and demonstrates that HDAC9 is one of critical components of a signal transduction pathway that links ischemic cerebral injury to reduced autophagy in experimental stroke." (PMID 26865248, 2016). "To date, only a handful of robust SNP associations have been identified for cardioembolic stroke (PITX2, ZFHX3), large-artery atherosclerotic stroke (9p21, HDAC9), and more recently, for all subtypes of stroke (12q24)." (PMID 25906364, 2015). "Epigenetic effects of selenium sources in protecting brain cells from stroke may involve histone deacetylase 9 (HDAC9), which leads to an increase in HIF-1 and a reduction in Sp1 protein levels by deacetylation and deubiquitination." (PMID 38251125, 2024). "Furthermore, the HDAC class IIa inhibitor TMP269 improves neurological score and infarct volume after stroke by reducing HDAC9 protein expression." (PMID 37324938, 2023). "Encouragingly, studies have also shown that HDAC9 is associated with the risk of stroke, while the action and mechanism of HDAC9 are not fully understood." (PMID 37250142, 2023). "We investigated the possible interaction between HDAC9 and transcriptional factors involved in stroke pathophysiology, that are able to activate in a sequence specific manner their target genes TfR1 22 and GPX4 26, such as HIF-1 and Sp1 in SH-SY5Y cells after OGD/Rx." (PMID 37324938, 2023). "An in vitro study showed that HDAC9 inhibition had neuroprotective effects on IS by inhibiting inflammation, which confirmed that depletion of HDAC9 could reduce cerebral injury in experimental stroke." (PMID 36833280, 2023). "Histone Deacetylase 9 inhibition therefore represents a potential drug target to reduce stroke." (PMID 35433850, 2022). "Although the rest of 16 causal genes identified by the integrative analysis were only replicated in one or two analyses, some of them (e.g. ALDH2, CDK6, HDAC9, and SLC44A2) were previously reported linked to stroke, which also demonstrate the reliability of our integrative analysis in a way." (PMID 35449099, 2022). "Interestingly, the class IIa HDACs inhibitor TMP269, by counteracting stroke-induced HDAC9 increase, reduces neuronal cell death and ameliorates general and neurological scores." (PMID 33513699, 2021). "For example, the HDAC9 locus was identified in GWAS on stroke, ACS, and PAD." (PMID 34943774, 2021). "The mechanisms though which HDAC9 can increase stroke risk were not defined, as well as its consequence on HDAC9 activities." (PMID 33513699, 2021). "Importantly, one type of HDAC, HDAC9, has been associated with stroke risk in several genome wide studies." (PMID 29321829, 2018). "By contrast, the HDAC9 and 9p21 associations were specific to large-vessel stroke, and not present with other stroke subtypes." (PMID 23041239, 2012). "Furthermore, since HDAC1 and 2, belonging to class I HDACs, and HDAC4 and 5, belonging to class II HDACs, increase in an in vitro model of stroke 30, 39, we investigate the specificity of HDAC9, among HDACs isoforms, in the modulation of TfR1 and GPX4 after ODG/Rx." (PMID 37324938, 2023). "Therefore, the development of drugs able to specifically inhibit HDAC9 overexpression or activity could represent a new pharmacological strategy to reduce ferroptosis and brain damage after stroke." (PMID 37324938, 2023). "However, the mechanisms linking the HDAC9 variant with increased stroke risk is still unclear due to the lack of relevant models to study the underlying molecular mechanisms." (PMID 35433850, 2022). "Whether HDAC9 plays a role during recovery after stroke is currently unknown." (PMID 28264471, 2017).
Stroke (continued). "In this study, we found that HDAC9 was up‐regulated in the ischaemic cerebral hemisphere after cerebral ischaemia/reperfusion (I/R) injury in rats and in vivo gene silencing of HDAC9 by recombinated lentivirus infection in the brain reduced cerebral injury in experimental stroke." (PMID 26865248, 2016). "Pharmacological targeting of HDAC9‐mediated signalling pathways at multiple levels may help design a new approach to develop therapeutic strategies for prevention of deterioration of cerebral function and for the treatment of stroke." (PMID 26865248, 2016). "In this study, we found that HDAC9 was up‐regulated in the ischaemic cerebral hemisphere after cerebral I/R injury in rats and in vivo gene silencing of HDAC9 by recombinated lentivirus infection and stereotaxic injection in the brain reduced cerebral injury in experimental stroke." (PMID 26865248, 2016). "Thus, HDAC9 inhibition could be a potential treatment for stroke." (PMID 40356977, 2025). "In the same year, and with a sample size of 16,851 cases and 32,473 non-stroke controls, the NINDS Stroke Genetics Network (SiGN) found a new locus associated with LAS close to TSPAN2 and confirmed the previous loci ABO, HDAC9, PITX2, and ZFHX3." (PMID 35743317, 2022). "In addition, the specific role of HDAC9 was determined by the silencing of this deacetylating enzyme that significantly reduced two ferroptotic markers, such as iron overload and 4-HNE, in temporoparietal cortex after stroke." (PMID 37324938, 2023). "Importantly, the shared stroke and CAD association signal rs2107595 near HDAC9 colocalized with TWIST1 but not HDAC9 expression in aorta." (PMID 31917787, 2020). "Furthermore, silencing of HDAC9 also prevented HIF-1 increase, Sp1 decrease, and consequently, the modulation of their target genes TfR1 and GPX4 in neurons in in vitro and in vivo models of stroke as demonstrated by Western blot and immunohistochemistry experiments." (PMID 37324938, 2023).
diabetes (75 papers, 2012 to 2025). "Previous studies have demonstrated that HDAC9 is associated with the pathogenesis of cardiometabolic diseases such as atherosclerosis and diabetes, and that global HDAC9 KO mice are protected against obesity-related metabolic disease." (PMID 36078104, 2022). "Because of the important role of HDAC9 in cell development and differentiation, dysregulated HDAC9 expression and activity have been associated with several human diseases including systemic autoimmunity, diabetes, the development of atherosclerotic plaques and cardiovascular disease." (PMID 34318404, 2021). "Because the expression of HDAC9 in diabetes is more sensitive to CI−AKI, this mechanism provides a therapeutic target and diagnostic marker for the treatment of CI−AKI in diabetes." (PMID 37175958, 2023). "Another link between HDAC9 and diabetes, metabolic and cardiovascular risks, has been proposed through the control of the circulating levels of the adipocyte-secreted adiponectin." (PMID 33513699, 2021). "Therefore, the GK SAAC genes Ide, Ppp1r3c, Hdac9, Ghsr and Gckr with their specific mutations, may change the protein functions and improve insulin sensitivity in the prediabetes stage in GK rats and act as anti-diabetics in GK rats." (PMID 30687391, 2018). "Additional indications point to a possible contribution of HDAC9 to diabetes." (PMID 33513699, 2021). "Interestingly, dysfunction or inhibition of some specific genes such as Ide, Ppp1r3c, Hdac9, Ghsr and Gckr can improve insulin sensitivity to varying degrees in pre-diabetes period in GK rats." (PMID 30687391, 2018). "HDAC9 regulates downstream gene expression by modulating chromatin conformation and transcription factor activity, participating in complex disease mechanisms including cardiovascular disorders, osteoporosis, obesity, diabetes-related complications, liver fibrosis, and various cancers." (PMID 41257548, 2025). "One SNP, rs12155400, reached genome-wide significant association with mild retinopathy in individuals of European ancestry without diabetes and hypertension, in the histone deacetylase 9 gene (HDAC9) gene on chromosome 7." (PMID 23393555, 2013).
atherosclerosis (71 papers, 2015 to 2025). A disease characterized by the build-up of fatty material and calcium deposition in the arterial wall resulting in partial or complete occlusion of the arterial lumen. "Aberrant HDAC expression is closely linked to atherosclerosis; for example, HDAC9 overexpression promotes vascular inflammation and plaque formation, whereas HDAC inhibitors ameliorate atherosclerotic lesions in experimental animals." (PMID 41562048, 2025). "HDAC9 encodes enzyme histone deacetylase 9, and has been implicated in progression of atherosclerosis through histone acetylation and subsequent expression of specific genes related to lipid metabolism and macrophage polarization." (PMID 40182431, 2025). "HDAC9, a class IIa histone deacetylase, has been implicated in various processes, including lipid metabolism, atherosclerosis progression, and macrophage polarization." (PMID 40948769, 2025). "A mouse model was developed in which the CRE variant rs2107595, which regulates HDAC9 expression and is associated with chronic inflammation and atherosclerosis, was deleted." (PMID 40867506, 2025). "In fact, the HDAC variant HDAC9 (allele 7p21.1) was shown to be associated with promoting atherosclerosis possibly by promoting plaque development and raising the risk of subsequent occurrence of thromboembolism." (PMID 39965251, 2025). "Deficiency of HDAC9 promotes cholesterol efflux from macrophages and reduces plaque area in atherosclerosis‐prone mice by enhancing the expression of ABCA1 and ABCG1." (PMID 39698913, 2024). "Among all the classical HDACs, HDAC9 is the most well-studied individual subtype for its association with atherosclerosis in animal and human models." (PMID 38001953, 2023). "Consistent with this, our group just completed a separate study showing the importance of Hdac9 in a mouse model of atherosclerosis, whereby knockout of Hdac9 in endothelial cells was associated with reduced burden of atherosclerosis." (PMID 35714152, 2022). "Increased HDAC9 mRNA levels have been identified in human carotid atherosclerotic plaques, and knockout of HDAC9 in a mouse model for atherosclerosis, the apolipoprotein E-deficient (ApoE-/-) mouse, was associated with reduced aortic atherosclerosis." (PMID 35433850, 2022). "Highlighting the value of our data-driven informatics pipeline, our original reason for embarking on this analysis of the HDAC9-associated CAD risk locus was to understand its role in governing the CAD- and atherosclerosis-causal effects of HDAC9." (PMID 35714152, 2022). "A previous study reported that HDAC9 deficiency in mice prevented neointimal formation induced by arterial ligation, providing further evidence of the gene’s contribution toward atherosclerosis and CHD." (PMID 35055468, 2022). "This is supported by several molecular studies that have documented a mechanistic role for HDAC9 as being causal for atherosclerosis and vascular calcification." (PMID 35714152, 2022). "In regard to the strong association of the gene with atherosclerosis, the HDAC9 rs2107595*A variant also showed increased CHD risk by 1.61-fold in a T2D Chinese population for AG + AA compared to GG genotypes." (PMID 35055468, 2022). "HDAC9 increases the risk of disease development by enhancing the atherosclerosis process in large- and small-caliber vessels." (PMID 34943774, 2021). "In conclusion, our study demonstrates a unique role for HDAC9 in contributing to vascular pathology by promoting EndMT, which is associated with increased atherosclerosis and an unstable plaque phenotype." (PMID 34338228, 2021). "In parallel, HDAC9 has been implicated in carotid intima-media thickness, large-vessel ischemic stroke, atherosclerosis, and atherosclerotic aortic calcification in humans." (PMID 34338228, 2021). "Endothelial-specific Hdac9 knockout is associated with reduced EndMT and a favorable plaque phenotype in atherosclerosis-prone mice." (PMID 34338228, 2021).
atherosclerosis (continued). "Of note, genome‐wide association study identifies a variant in HDAC9 associated with large vessel stroke, which would be consistent with the association with accelerating atherosclerosis." (PMID 34145738, 2021). "Further, deficiency of HDAC9 attenuates atherosclerosis in ApoE−/− mice." (PMID 29383092, 2017). "For instance, HDAC9 may increase the risk of vascular complications as HDAC9 has been implicated in aortic smooth muscle calcification, endothelial-mesenchymal transition, and increased aortic plaque lipid content in a mouse model of atherosclerosis." (PMID 41416997, 2025). "Therefore, the mechanism through which HDAC9 might cause atherosclerosis and CHD may be by influencing the TWIST1 gene activity." (PMID 35055468, 2022). "For instance, HDAC9 promotes endothelial-to-mesenchymal transition (EndMT), accelerating atherosclerosis progression, and contributes to diabetic retinopathy by regulating ANXA2-mediated EndoMT." (PMID 41257548, 2025). "Histone deacetylase 9 (HDAC9) is an atherosclerosis- and inflammation-promoting enzyme that activates NF-κB pathway signaling." (PMID 40863347, 2025). "Accordingly, HDAC9 has been widely studied in the context of metabolic disease, cardiovascular disease (with an emphasis on atherosclerosis and cardiac hypertrophy), immunity, and cancer, with a more recent appreciation of its relevance in placental biology." (PMID 41416997, 2025). "Accumulating evidence has highlighted the detrimental roles of HDAC9 in atherosclerosis, liver fibrosis, autoimmune disease, cancer, and Alzheimer’s disease in both humans and mice." (PMID 40002674, 2025). "By transplanting cells, the authors were able to show that the upregulation of Hdac9 in myeloid cells exacerbates atherosclerosis and worsens plaque destabilization." (PMID 40867506, 2025). "In mouse models of atherosclerosis and MI, HDAC (Histone Deacetylase 9) inhibition promoted reparative macrophage polarization and reduced inflammation, suggesting a role for HDACs in macrophage activation." (PMID 38170281, 2024). "Hdac9 is expressed in hematopoietic cells, and deletion of Hdac9 in the bone marrow protected hypercholesterolemic mice against the development of atherosclerosis." (PMID 38672510, 2024). "For example, VSMC-specific KO of HDAC9 is protective in an arterial stenosis model, and endothelial cells-specific KO of HDAC9 is protective in an atherosclerosis model." (PMID 38983721, 2024). "Inhibition of class IIa HDAC family members, blocked-EndMT-mediated gene induction, and endothelial HDAC9 knockout reduced atherosclerosis and enhanced plaque stability." (PMID 37371110, 2023). "Ox-LDL-induced endothelial cell apoptosis and inflammation are crucial periods in the progression of atherosclerosis and can be regulated by HDAC9." (PMID 36935751, 2023). "The literature also shows that HDAC9 is relevant to cerebrovascular diseases such as atherosclerosis." (PMID 37250142, 2023). "Atherosclerosis-prone mice showed reduced EndMT and significantly reduced plaque area while endothelial-specific HDAC9 knockout while endothelial-specific HDAC9 controlled EndMT and the atherosclerotic plaque phenotype." (PMID 38031118, 2023). "HDAC9 is also a regulator of atherosclerosis plaque stability and IKK activation to drive inflammatory responses in both endothelial and macrophages cells." (PMID 35280995, 2022). "This led the authors to conclude that rs2107595 is likely to contribute to atherosclerosis and CAD risk by regulating HDAC9 expression and gene-environment interactions." (PMID 35714152, 2022). "Previous studies have implicated inflammation as a possible pathway mediating the effect of HDAC9 on atherosclerosis." (PMID 35433850, 2022).
atherosclerosis (continued). "In vivo, atherosclerosis-prone mice with endothelial-specific Hdac9 knockout showed reduced EndMT and significantly reduced plaque area." (PMID 34338228, 2021). "So far, HDAC9 has been reported to affect several aspects of the pathogenesis of atherosclerosis, i.e. cholesterol efflux, platelet aggregation, interleukin 6 (IL-6) signaling, macrophage function, inflammation progression and vascular calcification." (PMID 32284067, 2020). "Thus, while constitutive loss of HDAC9 has been shown to protect from atherosclerosis in a mouse model and may be involved in regulating disease risk at this locus, our data link the rs2107595 haplotype with TWIST1 expression, suggesting a role for TWIST1 in human vascular disease." (PMID 31917787, 2020). "HDAC9 expression was assessed by immunohistochemistry in 30 ICA specimens from patients with ICA atherosclerosis > 75%, and the numerical areal density of HDAC9 positive cells was calculated." (PMID 32284067, 2020). "Genes IRAK4, HDAC9, ACSL1 and APPL159 are recently reported as atherosclerosis causing genes in T2DM patients." (PMID 28761062, 2017). "Accumulated evidence highlights the crucial roles of SNP rs2107595 and HDAC9 gene in the development of atherosclerosis." (PMID 27494404, 2016). "Inhibitors of HDAC3 and HDAC9 significantly reduced atherosclerosis in mouse models." (PMID 40076813, 2025). "In vivo, atherosclerosis-prone mice with endothelial-specific HDAC9 knockout showed reduced endothelial-to-mesenchymal transition, significantly reduced plaque area, and a more favorable plaque phenotype, with reduced plaque lipid content and increased fibrous cap thickness." (PMID 39281836, 2024). "Endothelial-specific KO of HDAC9 with Cdh5-Cre showed reduced plaque area and plaque lipid content, and increased fibrous cap thickness in an atherosclerosis model, suggesting that targeting HDAC9 may aid in the treatment of atherosclerosis." (PMID 38983721, 2024). "Researchers believe that targeted inhibition of HDAC9 may be a viable strategy to prevent atherosclerosis." (PMID 37762023, 2023). "Interestingly, HDAC9 contributes to the EndMT process and promotes the progression of atherosclerosis." (PMID 36935751, 2023). "While our study showed that the HDAC9-associated CAD risk locus does not cause CAD by modulation of HDAC9 levels, structure or function, our study does not suggest that HDAC9 is unimportant in causing atherosclerosis and CAD." (PMID 35714152, 2022). "The contribution of HDAC9 to atherosclerosis could also stem from a modulation of inflammatory cells." (PMID 33513699, 2021). "Together with other studies, our data argue strongly for the existence of a pathological HDAC9/EndMT/atherosclerosis axis and suggest that targeting of HDAC9 may be beneficial for plaque stabilization or slowing the progression of atherosclerotic disease." (PMID 34338228, 2021). "Collectively, we propose that these data suggest a pathological HDAC9/EndMT/atherosclerosis axis." (PMID 34338228, 2021). "Collectively, these findings indicate that in the setting of atherosclerosis, the absence of Hdac9 in endothelial cells is associated with reduced EndMT, reduced atherosclerotic burden, and a more favorable plaque phenotype." (PMID 34338228, 2021). "Indeed, HDAC4 regulates vascular inflammation via activation of autophagy in endothelial cells and the deletion of HDAC9 promotes inflammation resolution and reverse cholesterol transport in atherosclerosis and coronary heart diseases." (PMID 35059451, 2021). "Our study provides evidence for a pathological link among EndMT, HDAC9, and atherosclerosis and suggests that targeting of HDAC9 may be beneficial for plaque stabilization or slowing the progression of atherosclerotic disease." (PMID 34338228, 2021).